CYS1 (cystin 1)
Tractability: Antibody: its Gene Ontology location is reachable by antibodies, with medium confidence.
Gene: Protein-coding gene on chromosome 2 (10,056,473 to 10,080,944, reverse strand). Ensembl gene ENSG00000205795.
Subcellular location: Cell projection, cilium membrane; Cytoplasm, cytoskeleton, cilium axoneme
Pathways (Reactome):
Organelle biogenesis and maintenance: Trafficking of myristoylated proteins to the cilium
Gene Ontology:
Molecular function: protein binding
Cellular component: cilium; cytosol; axoneme; ciliary membrane
Genetic constraint (gnomAD): Loss-of-function variants: 5 observed, 4.48 expected, observed/expected ratio (o/e) 1.12, 90% interval 0.56 to 1.86. That is too few expected variants to judge how well the gene tolerates losing a copy. Missense variants: 218 observed, 143.02 expected, observed/expected ratio (o/e) 1.52, 90% interval 1.36 to 1.71. Synonymous variants: 83 observed, 60.24 expected, observed/expected ratio (o/e) 1.38, 90% interval 1.15 to 1.65.
Gene-disease validity (ClinGen):
ClinGen rates the evidence that CYS1 causes each of these diseases.
polycystic kidney disease (autosomal recessive): Limited. A usually autosomal dominant and less frequently autosomal recessive genetic disorder characterized by the presence of numerous cysts in the kidneys leading to end-stage renal failure.
Homologues: Orthologues: chimpanzee CYS1 (96% identical), macaque CYS1 (91% identical), pig CYS1 (61% identical), dog CYS1 (60% identical), rat Cys1 (57% identical), mouse Cys1 (56% identical).
Diseases named in the same sentence as CYS1 in open-access papers:
CYS1 is named in the same sentence as 14 diseases in open-access papers, as found by Europe PMC text mining. Sharing a sentence is not in itself a finding about the gene and the disease. The quoted sentences say what the papers report.
cystic kidney disease (5 papers, 2015 to 2024). A congenital or acquired kidney disorder characterized by the presence of renal cysts. "CYS1 mutation on chromosome 2p25 has been proven to be a candidate for recessive cystic kidney disease." (PMID 37025600, 2023). "Mutation of the Cys1 gene underlies the renal cystic disease in the Cys1cpk/cpk (cpk) mouse that phenocopies human autosomal recessive polycystic kidney disease (ARPKD)." (PMID 34521872, 2021). "Mutations in the gene encoding hepatocyte nuclear factor-1-beta (HNF1B) cause cystic kidney disease, and HNF1B has been shown to regulate expression of several cystogenic genes, including Pkhd1 and Cys1." (PMID 36710876, 2022). "Since the protein product of Cys1 localizes to primary cilium together with most genes involved in renal cystic disease, localization of the Kif12 protein product to primary cilia provides further support for this gene as an Mpkd2 locus candidate." (PMID 26295839, 2015). "Based on this unique case, we analyzed ES data from 521 individuals with pediatric onset cystic kidney disease to identify additional families with deleterious variants in the CYS1 locus but did not identify any additional cases." (PMID 34521872, 2021).
diabetes (1 paper, 2024). "To confirm this, we then analyzed several known clock-controlled genes for the retina (Adcy1, Drd4, Nr2e3, Cys1, Plekbh1, Usp2) that also showed amplitude changes but no phase changes, indicating that the retinal clock was entrained to the 12L:12D cycle at this stage of diabetes." (PMID 38039846, 2024).
renal failure (1 paper, 2018). "cpk mice harbor a homozygous mutation in cys1, which encodes the cilia-associated protein, cystin, and exhibit rapidly-progressing cystic disease that leads to renal failure and death typically by 3 weeks of age22–24." (PMID 29463793, 2018).
cancer (1 paper, 2019). A tumor composed of atypical neoplastic, often pleomorphic cells that invade other tissues. "The 13 overexpressed genes were reported to play a role in RCC: PAX2, NAT8, GBA3, SLC22A2 other cancer types: AOC1, HAO2, TMEM27, cell death (NPR3) or kidney metabolism: TMEM171, CYS1." (PMID 31150395, 2019).
CYS1 also shares sentences with these, for which no sentence is quoted: autosomal recessive polycystic kidney disease (4 papers); Blindness (1); cardiovascular diseases (1); chronic sinusitis (1); ciliopathy (1); cystic kidney (1); epilepsy (1); liver fibrosis (1); nephronophthisis (1); viral infection (1).